RUSC1 (RUN and SH3 domain containing 1)
Description:
Associates with the adapter-like complex 4 (AP-4) and may therefore play a role in vesicular trafficking of proteins at the trans-Golgi network. Signaling adapter which plays a role in neuronal differentiation. Involved in regulation of NGF-dependent neurite outgrowth. May play a role in neuronal vesicular trafficking, specifically involving pre-synaptic membrane proteins (By similarity). Seems to be involved in signaling pathways that are regulated by the prolonged activation of MAPK. Can regulate the polyubiquitination of IKBKG and thus may be involved in regulation of the NF-kappa-B pathway.
Synonyms: Nesca
Tractability: PROTAC: UniProt records ubiquitination sites on it; ubiquitination databases record sites on it.
Gene: Protein-coding gene on chromosome 1 (155,320,739 to 155,331,118, forward strand). Ensembl gene ENSG00000160753.
Subcellular location: Cytoplasm; Nucleus; Cytoplasm, cytoskeleton; Cytoplasmic vesicle; Early endosome; Postsynaptic density; Golgi apparatus
Subcellular location (Human Protein Atlas): Cytosol; Nucleoplasm; Vesicles
Gene Ontology:
Molecular function: protein binding; actin binding
Biological process: protein polyubiquitination
Cellular component: cytoplasm; cytosol; nucleus; cytoplasmic vesicle; early endosome; Golgi apparatus; microtubule cytoskeleton; postsynaptic density; cytoskeleton
Genetic constraint (gnomAD): Loss-of-function variants: 40 observed, 72.68 expected, observed/expected ratio (o/e) 0.55, 90% interval 0.43 to 0.72. The upper end of that interval is the gene's LOEUF score, 0.72, which puts it in group 2 of 6, group 1 being the genes least tolerant of losing a copy. Missense variants: 1,090 observed, 1,172.1 expected, observed/expected ratio (o/e) 0.93, 90% interval 0.88 to 0.98. Synonymous variants: 506 observed, 491.47 expected, observed/expected ratio (o/e) 1.03, 90% interval 0.96 to 1.11.
Homologues: Orthologues: chimpanzee RUSC1 (99% identical), macaque RUSC1 (98% identical), pig RUSC1 (89% identical), guinea pig RUSC1 (85% identical), rat Fdps (84% identical), mouse Rusc1 (84% identical), dog RUSC1 (82% identical), zebrafish rusc1 (20% identical). Paralogues in human: RUSC2 (27% identical).
Diseases named in the same sentence as RUSC1 in open-access papers:
RUSC1 is named in the same sentence as 3 diseases in open-access papers, as found by Europe PMC text mining. Sharing a sentence is not in itself a finding about the gene and the disease.
RUSC1 shares sentences with these, for which no sentence is quoted: COVID-19 (1 paper); hepatocellular carcinoma (1); lung carcinoma (1).